EVI5 (ecotropic viral integration site 5)
Description:
Functions as a regulator of cell cycle progression by stabilizing the FBXO5 protein and promoting cyclin-A accumulation during interphase. May play a role in cytokinesis.
Synonyms: EVI-5; NB4S
Tractability: PROTAC: UniProt records ubiquitination sites on it; ubiquitination databases record sites on it; its protein half-life has been measured.
Gene: Protein-coding gene on chromosome 1 (92,508,696 to 92,792,416, reverse strand). Ensembl gene ENSG00000067208.
Subcellular location: Nucleus; Cytoplasm, cytoskeleton, microtubule organizing center, centrosome; Cytoplasm, cytoskeleton, spindle
Subcellular location (Human Protein Atlas): Golgi apparatus; Vesicles
Gene Ontology:
Molecular function: GTPase activator activity; protein binding; small GTPase binding
Biological process: positive regulation of GTPase activity; regulation of cilium assembly; retrograde transport, endosome to Golgi
Cellular component: cytosol; centrosome; nucleus; spindle
Genetic constraint (gnomAD): Loss-of-function variants: 19 observed, 37.6 expected, observed/expected ratio (o/e) 0.51, 90% interval 0.35 to 0.74. The upper end of that interval is the gene's LOEUF score, 0.74, which puts it in group 3 of 6, group 1 being the genes least tolerant of losing a copy. Missense variants: 378 observed, 435.24 expected, observed/expected ratio (o/e) 0.87, 90% interval 0.8 to 0.95. Synonymous variants: 138 observed, 152.67 expected, observed/expected ratio (o/e) 0.9, 90% interval 0.79 to 1.04.
Homologues: Orthologues: macaque EVI5 (99% identical), rabbit EVI5 (97% identical), pig EVI5 (96% identical), chimpanzee EVI5 (94% identical), rat Evi5 (90% identical), guinea pig EVI5 (88% identical), dog EVI5 (86% identical), mouse Evi5 (85% identical), tropical clawed frog evi5 (85% identical), zebrafish evi5b (70% identical). Paralogues in human: EVI5L (68% identical), TBC1D10B (17% identical), RABGAP1 (16% identical), TBC1D4 (16% identical), RABGAP1L (16% identical), TBC1D1 (16% identical), TBC1D9B (16% identical), USP6NL (16% identical), TBC1D9 (15% identical), TBC1D8 (15% identical), TBC1D10A (14% identical), TBC1D10C (14% identical), and 33 more.
Diseases named in the same sentence as EVI5 in open-access papers:
EVI5 is named in the same sentence as 18 diseases in open-access papers, as found by Europe PMC text mining. Sharing a sentence is not in itself a finding about the gene and the disease. The quoted sentences say what the papers report.
laryngeal carcinoma (4 papers, 2020 to 2023). Carcinoma that arises from the laryngeal epithelium. "Another study has disclosed that the oncogene Ecotropic viral integration site 5 (Evi5) accelerates laryngeal cancer cell proliferation by counteracting FBXW7, thus facilitating the accumulation of its substrate c-MYC." (PMID 35515121, 2022).
Autoimmunity (1 paper, 2019). The occurrence of an immune reaction against the organism's own cells or tissues. "Several genes, such as TREX1, FLI1, EVI5, IL1RAPL1, are known for their role in autoimmunity, with EVI5 being an established MS risk gene, whereas others, such as CBFB, OPCML and KMT2A, are involved in lymphoproliferative disorders (OMIM)." (PMID 30541027, 2019).
bladder cancer (1 paper, 2020). "In recent years, EVI5, an important protein regulating cell cycle and migration, has been increasingly reported to be associated with HCC, bladder cancer, melanoma, leukemia, lymphoma and many other tumors." (PMID 32393392, 2020).
developmental delays (1 paper, 2024). "Further, ferritin-injection rescued developmental delays associated with Evi5-depletion." (PMID 38744835, 2024).
laryngeal squamous cell carcinoma (1 paper, 2020). A squamous cell carcinoma that arises from the larynx. "However, the expression and biological function of Evi5 in human laryngeal squamous cell carcinoma (LSCC) are still unknown." (PMID 32047362, 2020).
multiple sclerosis (1 paper, 2024). A progressive autoimmune disorder affecting the central nervous system resulting in demyelination. "In humans, Evi5 is a high-risk locus for multiple sclerosis, a debilitating disease that also presents with excess iron in the CNS." (PMID 38744835, 2024). "To summarize, our findings show that Evi5 is critical for intracellular iron trafficking via transferrin-1 and ferritin, and implicate altered iron homeostasis in the etiology of multiple sclerosis." (PMID 38744835, 2024).
neuroblastoma (1 paper, 2007). Neuroblastoma (NB) is the most common solid, extracranial childhood tumor. "The Evi5 chromosomal locus is frequently targeted for recombination in several cancers and a truncated Evi5 is expressed in a patient with neuroblastoma." (PMID 17319958, 2007).
porphyria (1 paper, 2024). Porphyria is a group of diseases in which substances called porphyrins build up, negatively affecting the skin or nervous system. "Tsf1 delivers iron to target tissues and is sufficient to rescue the porphyria phenotype in AGBE-depleted PGs, but not when Evi5 is impaired." (PMID 38744835, 2024).
cancer (10 papers, 2007 to 2024). A tumor composed of atypical neoplastic, often pleomorphic cells that invade other tissues. "Ample evidence showed that EVI5 expression was elevated in human cancers, while the underlying mechanisms are poorly understood." (PMID 32393392, 2020). "The deregulated expression of Evi5 has also been observed in several kinds of cancers, indicating a tumor promoting function of Evi5." (PMID 32047362, 2020). "RECK is known to suppress migration and invasion of cancer cells, but the function of EVI5 is less clear." (PMID 25537516, 2015). "Therefore, EVi5 can be a potential oncogene, and misregulation of Evi5 levels has been found in several cancer types." (PMID 34354043, 2021). "Evi5 has been shown to be dysregulated in several cancer types." (PMID 32047362, 2020). "The co-expression of EVI5 and Emi1 has been reported in other types of cancers." (PMID 32393392, 2020). "However, although Evi5 has been found to be overexpressed in certain cancer types, direct evidence for its role as an oncogene is still missing." (PMID 32047362, 2020). "This protein interacts with Evi5 and has a potential role in cancer." (PMID 20102610, 2010). "The administration of TGF-β1 increased the migration and invasion of EVI5-knockout NSCLC cells, and increased the levels of p-Smad3 and its downstream signaling molecules, indicating a therapeutic role for EVI5 in inhibition of cancer metastasis." (PMID 32393392, 2020).
tumor (5 papers, 2014 to 2023). "Knockdown of EVI5 in vitro inhibited tumor cell proliferation, migration and invasion in NSCLC cells." (PMID 32393392, 2020). "In the present study, we addressed the role of EVI5 in NSCLC by regulating tumor growth, migration and invasion." (PMID 32393392, 2020). "In the tumor-bearing nude mice, The transplanted tumors originated from Evi5-KO TU212 cells were significantly decreased when compared with control TU212 cells." (PMID 32047362, 2020). "Tumor 324 contained only a single integration at the Gfi1/Evi5 locus however it contained two integrations at the Myc/Pvt1 locus." (PMID 24886479, 2014). "Tumor 327 contained six interspersed integrations at the Gfi-1/Evi-5 locus, while tumor 410 contained two integrations at this locus." (PMID 24886479, 2014). "While the four tumors harbored integrations in Gfi1 and ecotropic viral-integration Site 5 (Evi5) (the Gfi1/Evi5 locus), tumor 359 contained six integrations at this locus, four of which were positioned in sense in the 3′-UTR of Gfi1." (PMID 24886479, 2014). "Furthermore, as a GTPase that regulates intracellular transport, membrane trafficking, cytokinesis, and cell migration, the tumor promoting metastasis role of EVI5 is poorly understood." (PMID 32393392, 2020). "To clarify the cellular mechanism underlying EVI5-mediated tumor progression, we established stable EVI5-knockout NSCLC cell lines (EVI5-KO cells), this was confirmed by the barely expressed level of EVI5 protein expression in EVI5-KO cells compared to that in vector transfected cells (Cas-9 cells)." (PMID 32393392, 2020). "The effect of Evi5 on LSCC tumor growth in vivo was studied in a tumor xenograft model in mice." (PMID 32047362, 2020). "To clarify the mechanism underlying EVI5-mediated tumor metastasis, we analyzed the molecular expression of TGF-β receptor II, TGF-β receptor I, p-Smad3, Snail, Vimentin, MMP2 and N-Cadherin levels were significantly decreased and E-Cadherin was significantly increased in EVI5-knockdown cells." (PMID 32393392, 2020). "The transplanted tumors originated from Evi5-knockout TU212 cells were significantly decreased when compared with control TU212 cells, as revealed by measuring tumour mass." (PMID 32047362, 2020). "For a better understanding of the role of RECK and EVI5 in miR-135b-mediated tumor invasion, we first examined the expression and function of RECK and EVI5 in HCC." (PMID 25537516, 2015). "EVI5 could promote collective cell migration through its Rab-GAP activity, the mechanism by which it regulates tumor metastasis remains unclear." (PMID 32393392, 2020).
neurodegenerative disease (1 paper, 2025). A disorder of the central nervous system characterized by gradual and progressive loss of neural tissue and neurologic function. "Twenty-seven of these associations are known disease loci reported in GWAS, including APOE, MME, CD2AP, CD33 and IL34 for AD, and CD40, CD58, EVI5, IL7R and STAT3 for MS, and 23 associations represent previously unreported genetic associations with neurodegenerative diseases." (PMID 40037332, 2025).
EVI5 also shares sentences with these, for which no sentence is quoted: hepatocellular carcinoma (3 papers); leukemia (1); lymphoma (1); lymphoproliferative disorders (1); melanoma (1); non-small cell lung carcinoma (1); T-cell lymphomas (1).